PLIN3 (perilipin 3)
Diseases named in the same sentence as PLIN3 in open-access papers (continued):
Sharing a sentence is not in itself a finding about the gene and the disease.
tumor (continued). "Finally, immunohistochemical staining of tumor sections for PLIN3 (a lipid droplet marker) confirmed higher lipid droplet levels in HCT116 FR tumors than in parental tumors and decreased lipid droplet levels in iDGAT-treated tumors." (PMID 38167301, 2024). "Spotted LDs-like PLIN3 staining was dominantly enriched in tumor cells than other cell types." (PMID 38554152, 2024). "Collectively, high PLIN3+ tumor cells might result in the exhaustion of T cells in peripheral blood." (PMID 38554152, 2024). "We hypothesized that high intracellular PLIN3 expression promoted tumor cell growth; however, for immune cells, it enhanced the antitumor immune efficacy of CD8+ T lymphocytes." (PMID 38554152, 2024). "The first goal of our study was to analyze the incidence of LDs (via p-phenylenediamine staining and assessing the LD coating PLIN1, PLIN2, PLIN3) and size of LDs (via transmission electron microscopy) in canine OS tumor specimens derived from patients after surgery or necropsy." (PMID 35834072, 2022). "Similarly, ACSS3 regulated TG and cholesterol contents in tumor cells through PLIN3-dependent signaling." (PMID 33391508, 2021). "Furthermore, PLIN3 inhibited CD8+ T cells infiltration not only in the tumor microenvironment but also in circulating lymphocytes, which might be regulated by B7-H2." (PMID 38554152, 2024). "Altogether these data indicated that PLIN3 was upregulated in OSCC tissues and high PLIN3+ tumor cells may lead to immunosuppression through T cell exhaustion, accompanied by infiltration of PLIN3+ fibroblasts, thus collaboratively promoting tumor progression and predicting inferior patient outcome." (PMID 38554152, 2024). "Notably, we also observed that patients with PLIN3high tumor cells were strongly correlated with poor differentiation and high PLIN3+ fibroblasts showed advanced T stage, suggesting that PLIN3 in OSCC might promote malignant progression." (PMID 38554152, 2024). "Heatmap analysis showed marked upregulation of PLIN3, whereas LIPG, DGAT2, CIDEC, and PLIN1 were down-regulated in tumor tissues and GbPDTOs compared to those in normal tissues." (PMID 41376821, 2025). "We determined mRNA expression profiles of PLIN1, PLIN2, PLIN3, PLIN4, and PLIN5 in a panel of OC cell lines and tumor tissue, using RT‐PCR." (PMID 41041279, 2025). "Interestingly, OSCC patients with PLIN3high tumor cells exhibited a higher Ki-67 positivity contrary to immunocytes, and we speculate that PLIN3 was as important as LDs for the growth of tumor cells, but also indispensable for immune cells in the activation of CD8+ T lymphocytes." (PMID 38554152, 2024). "So, we conducted LC/MS to evaluate androgen synthesis in tumor cells, which was the level of testosterone (T) and dihydrotestosterone (DHT) contents in C4-2 cells stably overexpressing ACSS3 and/or knocking down PLIN3." (PMID 33391508, 2021). "High PLIN3 expression was negatively correlated with ACSS3 expression and positively correlated with tumor stage and Gleason score." (PMID 33391508, 2021). "To determine the expression of ACSS3, PLIN3, BIP, PERK in tumor tissues, we conducted IHC staining in tumors." (PMID 33391508, 2021). "Given that ACSS3 promoted PLIN3 protein degradation, we reasoned that PLIN3 is required for ACSS3-mediated tumor suppression." (PMID 33391508, 2021). "Thus, we divided OSCC patients into different subpopulations based on PLIN3 and B7-H2 expression, and OSCC patients with high PLIN3+B7-H2+ tumor cells had significantly shorter OS and DFS and harbored less absolute count of CD3+CD8+ and CD3+CD4+ T cell infiltration in peripheral blood." (PMID 38554152, 2024). "Correlation between protein expression levels of PLIN3 and clinicopathological variables was evaluated in patients with OSCC, such as postoperative recurrence, distant metastasis, sex, age of patients, as well as tumor node metastasis (TNM) stage, T stage, N stage, and differentiation." (PMID 38554152, 2024).
tumor (continued). "Negative correlations across those tumor types were observed in four target genes (ARPC2, CFL1, PLIN3, RAP1GDS1)." (PMID 39201394, 2024). "The results demonstrated that the mRNA levels of PLIN1/PLIN4/PLIN5 were not correlated with tumor recurrence status, while PLIN2 and PLIN3 were correlated with tumor recurrence status." (PMID 37189627, 2023). "Immunofluorescence for PLIN1 showed no signal within the tumor, whereas PLIN2 positive cells were seen adjacent and within the necrotic region and PLIN3 was restricted to the necrosis surrounding area." (PMID 35834072, 2022). "Then compared with overexpressed PLIN3, overexpressed ACSS3+PLIN3 did not affect cell proliferation, migration, LD deposition area, TG and cholesterol content, indicted that PLIN3 rescued the ACSS3-mediated tumor cell suppression function." (PMID 33391508, 2021).
cancer (10 papers, 2020 to 2025). A tumor composed of atypical neoplastic, often pleomorphic cells that invade other tissues. "Recent pan-cancer studies reveal that molecular alterations like PLIN3/EPHB2 dysregulation and hypoxia-related signatures consistently promote M2 macrophage infiltration and immunosuppression, correlating with adverse outcomes across malignancies." (PMID 41220948, 2025). "Similar to previous studies, we demonstrated that PLIN3 was upregulated and predicted a poor prognosis in OSCC, suggesting that PLIN3 accumulated in cells to serve as a conservative oncogene to promote cancer development." (PMID 38554152, 2024). "Overexpression of PLIN2 and PLIN3 has been observed in a number of cancers and often correlates with higher cellular proliferation and poor prognosis." (PMID 39297796, 2024). "The correlation between the expression of PLIN3 and the pathological stage of cancer was observed through the “pathological stage map” module of HEPIA2." (PMID 37503320, 2023). "PLIN3 gene expression increased after incubation with a mix of sera from cancer patients (PLIN3 = 0.72 ± 0.08 vs. 0.89 ± 0.08 (p < 0.001) for the control group and cancer group, respectively)." (PMID 36980729, 2023). "Cancer cases were divided into high expression group and low expression group according to the expression level of PLIN3, and the correlation between the expression of PLIN3 and the prognosis of HCC patients was studied using TCGA data set." (PMID 37503320, 2023). "However, the correlation between PLIN3 expression and patient prognosis varies among different cancer types." (PMID 41041279, 2025). "However, for many years, the study of PLIN2 and PLIN3 in cancer was restricted to descriptions in different tumors." (PMID 38554152, 2024). "They suggested that PLIN1, PLIN2, and PLIN3 may be involved in cancers such as hepatocellular adenoma and carcinoma, sebaceous adenoma and carcinoma, and lipoma tumors, while PLIN5 was excluded as not sufficient proof was given." (PMID 34067931, 2021). "In addition to these widely studied proteins, there were still several proteins whose roles in cancer were unclear such as PLCX3, PHYHD1 and PLIN3, which provided a new direction for cancer research." (PMID 33200655, 2020). "The remaining eight target genes (CFL1, FNBP4, NDUFB3, OCIAD2, PLIN3, POU2AF1, RAC1, TMEM141) presented a combined influence in five or fewer cancer types." (PMID 39201394, 2024). "ACSL3, AIFM2, HSD17B7, LPCAT1, LSS, PLIN3 and RAB10 were up-regulated with the progression of cancer stage of HCC patients, while CIDEB, G0S2, HSD17B13, PLIN1 and PLIN2 were down-regulated." (PMID 37464334, 2023).
infection (4 papers, 2020 to 2025). The state of being infected such as from the introduction of a foreign agent such as serum, vaccine, antigenic substance or organism. "Cells were transduced with lentiviral vectors expressing Cas9 and a scramble control (sgCtrl) or PLIN3-specific sgRNA (sgPLIN3), followed by infection with HIV-1 at an MOI of 1 for 96 h." (PMID 41085277, 2025). "Furthermore, we observed an upregulation of PLIN3 by infection and a downregulation by CGS21680." (PMID 39005937, 2024). "Furthermore, qPCR analysis revealed that H19 overexpression in hepatocytes led to the increased expression of numerous genes involved in lipid synthesis and storage, such as Gpam, Mogat, Fasn, Acaca, Apoc3, Srebp, Plin2, Plin3, Lipe and Mlxipl at 72 hours after Ad‐H19 infection." (PMID 31809000, 2020). "Together, these results suggest that the increase in PLIN3 mRNA levels observed upon infection of primary CD4+ T cells is not due to increased stability of the transcript." (PMID 41085277, 2025).
skin disorder (1 paper, 2025). Any deviation from the normal structure or function of the skin or subcutaneous tissue that is manifested by a characteristic set of symptoms and signs. "Despite their expression in the epidermis, mutations in either PLIN2 or PLIN3 have not been linked to Mendelian skin disorder in humans so far." (PMID 40818613, 2025).
PLIN3 also shares sentences with these, for which no sentence is quoted: pancreatic cancer (3 papers); viral infection (2); brain ischemia (1); cervical squamous cell carcinoma (1); colon cancer (1); Dengue virus infection (1); diabetes (1); dissection (1); epithelioid sarcoma (1); esophageal squamous cell carcinoma (1); Ewing sarcoma (1); fibrosarcoma (1); hyperprolinemia type 2 (1); inflammatory skin disease (1); Kawasaki disease (1); leiomyosarcoma (1); lipodystrophy (1); liver cancer (1); melanoma (1); metabolic disease (1); metabolic syndrome (1); myeloma (1); ovarian carcinoma (1); rhabdomyosarcoma (1); Seizure (1); Sepsis (1); undifferentiated sarcomas (1).